TRIM50 (tripartite motif containing 50)
Diseases named in the same sentence as TRIM50 in open-access papers (continued):
Sharing a sentence is not in itself a finding about the gene and the disease.
tumor (11 papers, 2018 to 2025). "Functionally, overexpression of TRIM50 suppressed GC cell proliferation and indirectly mitigated the invasion and migration of GC cells by inhibiting the M2 polarization of tumor-associated macrophages (TAMs)." (PMID 38993561, 2024). "To further elucidate the underlying mechanisms, we initially observed that TRIM50 effectively inhibits glucose uptake and ATP generation in GC cells, thereby reducing the amount of energy synthesis needed for tumor cell proliferation." (PMID 38993561, 2024). "Altogether, both of our gain-of-function model and loss-of-function model support the conclusion that TRIM50 could act as a tumor suppressor to inhibit malignant behaviors of HCC cells." (PMID 29789583, 2018). "Addressing these limitations and conducting more comprehensive studies will contribute to a better understanding of the role of TRIM50 in GC and its regulation within the tumor microenvironment, as well as its potential therapeutic implications." (PMID 38993561, 2024). "In this study, we observed a significant downregulation of TRIM50 in GC tissues, which correlated closely with tumor size, distant metastasis, and TNM staging." (PMID 38993561, 2024). "Tripartite motif-containing protein 50 (TRIM50) is a recently discovered E3 ubiquitin ligase that participates in tumor progression." (PMID 39538371, 2024). "Mechanistically, TRIM50 inhibited tumor development by targeting junction plakoglobin (JUP), a transcription factor, for degradation mediated by K63-linked ubiquitination at the K57 site." (PMID 39768197, 2024). "Specifically, CD8+ T cells, dendritic cells, macrophages, NK cells, and Th1 cells in the tumor microenvironment were effectively recruited through activating TRIM50." (PMID 39538371, 2024). "TRIM50 has been proved to achieve its tumor inhibition function in a variety of cancers through ubiquitination mediated by its RING domain." (PMID 39538371, 2024). "In vivo, TRIM50 overexpression inhibited tumor growth in a subcutaneous xenograft model, while its knockdown showed the opposite effect." (PMID 39768197, 2024). "We steadily probed into TRIM50 expression’s association with malignancy behavior of TNBC, specific anti-tumor mechanism, as well as interaction protein in TNBC." (PMID 39538371, 2024). "This demonstrates that TRIM50 enhances tumor aggressiveness by directly increasing β-catenin levels, activating the Wnt/β-catenin pathway." (PMID 39768197, 2024). "Multiple studies have demonstrated the significant role of TRIM50 in tumorigenesis and tumor progression." (PMID 38993561, 2024). "In this report, the results confirmed that the upregulation of TRIM50 formed an inflammatory tumor microenvironment and activated the immune response in BC." (PMID 39538371, 2024). "The subcutaneous xenograft tumor model and metastasis models confirmed the reversal of the inhibitory effects of TRIM50 on GC growth and metastasis by restoring PGK1 expression." (PMID 38993561, 2024). "TRIM50 overexpression displayed inhibitory effects on tumor proliferation and metastasis in GC via regulating β-catenin degradation." (PMID 36046365, 2022). "In in vivo assay, TRIM50 overexpression inhibited tumor growth and blocked the Wnt/β-catenin signaling pathway." (PMID 36046365, 2022). "Another research has demonstrated that TRIM50 is a tumor suppressor in ovarian cancer by reducing Src activity." (PMID 36046365, 2022). "In our study, a series of in vitro and in vivo experiments showed that TRIM50 overexpression suppressed cell proliferation and tumor growth, and induced cell apoptosis." (PMID 34568024, 2021). "Gain- and loss-of-function experiments in SKOV3 and A2780 cell lines have also demonstrated that TRIM50 is required for proliferation and migration of OC cells in vitro, as well as for tumor growth in xenograft models in vivo." (PMID 34208621, 2021).
tumor (continued). "The tumor suppressive function of TRIM50 is, at least partly, explained by TRIM50-mediated ubiquitination and proteasomal degradation of Src, a proto-oncogene whose expression is correlated with poor prognosis in multiple cancer types." (PMID 34208621, 2021). "Then, we used the nude mouse xenograft model to validate the effect of TRIM50 overexpression on tumor growth in vivo." (PMID 34568024, 2021). "As a result, similar results were obtained from IHC staining experiments, showing TRIM50 downregulation in tumor tissues." (PMID 34568024, 2021). "Two of them (TRIM16 and TRIM50) are considered tumor suppressive, while others (TRIM11, TRIM25, TRIM27, TRIM52 and TRIM59) instead promote oncogenesis in this type of cancer." (PMID 34208621, 2021). "In a xenograft tumor model, TRIM50 showed an antitumor effect in hepatocarcinoma, as it acts as a tumor suppressor by directly targeting Snail1and reversing EMT." (PMID 33114139, 2020). "In the study, we detected the expression of TRIM50 in clinical HCC specimen, analyzed the correlation of TRIM50 expression with disease progression, and further investigated its role in tumor growth, migration, and invasion of HCC cells." (PMID 29789583, 2018). "When visible tumor appeared, we injected TRIM50 expression plasmid to the left flanks and mock control to the right flanks of the mice." (PMID 29789583, 2018). "The growth kinetics of the formed tumor showed that transfection of TRIM50 significantly inhibited tumor growth." (PMID 29789583, 2018). "All these data revealed that TRIM50 acted as a tumor suppressor in HCC via directly targeting SNAIL and reversing epithelial-to-mesenchymal transition (EMT) process." (PMID 29789583, 2018). "To further assess the antitumor effect of TRIM50 in vivo, we constructed xenograft tumor models by injection of BEL7402 cells to both flanks of nude mice." (PMID 29789583, 2018). "In this study, we identified the tumor-suppressor role of TRIM50 in the development of HCC and further clarified its involved molecular mechanism for the first time." (PMID 29789583, 2018). "Thus, we established a xenograft tumor model to evaluate the effect of TRIM50 on carcinogenesis of TNBC in vivo." (PMID 39538371, 2024). "In concert with the results evidenced by the CCK8, colony formation experiments that tumors with TRIM50 upregulation had a lower proliferation capacity, the growth curve displayed that the overexpression of TRIM50 significantly inhibited tumor volume (p < .001)." (PMID 39538371, 2024). "In addition, TRIM50 suppressed glycolysis and tumor progression by mediating ubiquitination and degradation of Phosphoglycerate Kinase 1 (PGK1), a key enzyme in the glycolytic pathway." (PMID 39768197, 2024). "Furthermore, we measured the role of TRIM50 overexpression on tumor growth as well as the Wnt/β-catenin signaling pathway in vivo." (PMID 36046365, 2022). "In addition, IHC staining of Ki-67 was performed to evaluate tumor growth and showed that the TRIM50-overexpressing group had lower proliferative indexes than the vector control group." (PMID 34568024, 2021). "TRIM50 suppresses cell proliferation and tumor growth and induces cell apoptosis." (PMID 34568024, 2021). "As our data showed the effective suppression of SNAIL by TRIM50 in HCC cells, we are further interested to define whether TRIM50 acts as a tumor suppressor through its suppression of SNAIL-mediated EMT process." (PMID 29789583, 2018). "In vivo assay by xenograft tumor model verified the antitumor effect of TRIM50 on HCC." (PMID 29789583, 2018). "Notably, we observed lower TRIM50 expression and increased M2 macrophage infiltration in primary tumors of GC patients with metastasis compared to those without metastasis, highlighting a potential role for TRIM50 in the modulation of the tumor immune microenvironment and the GC progression." (PMID 38993561, 2024).
tumor (continued). "Taken together, these results showed that TRIM50 acted as a tumor suppressor in HCC cells by directly targeting SNAIL and reversing EMT, which further indicated that positive modulation of TRIM50 might be a novel therapeutic strategy for SNAIL overexpressed HCC cells." (PMID 29789583, 2018). "Thus, we are interested to know whether overexpression of SNAIL could rescue the tumor-suppressor role of TRIM50." (PMID 29789583, 2018). "TRIM50 promoted the infiltration of CD8 T cells, Macrophage, and NK cells in BC, shaping the inflammatory tumor microenvironment." (PMID 39538371, 2024). "Previous studies have elucidated that TRIM21, TRIM26, TRIM35, TRIM50, and TRIM56 acted as tumor suppressors by inhibiting tumor cell proliferation, and TRIM3, TRIM16, TRIM21, TRIM25, and TRIM26 negatively regulated migration and invasion in HCC cells." (PMID 35142083, 2022). "Clinical pathological parameters showed a negative correlation between TRIM50 expression and tumor volume, distant metastasis, and TNM staging." (PMID 38993561, 2024). "Second, the direct demonstration of the inhibitory effect of TRIM50 on GC metastasis was limited by the absence of an in vivo mouse model of orthotopic tumor metastasis in this study." (PMID 38993561, 2024). "In vivo experiments confirmed the inhibitory effect of TRIM50 on GC tumor growth, supported by IHC staining showing a negative correlation between TRIM50 and Ki-67 expression." (PMID 38993561, 2024). "Subsequently, protein semiquantification analysis of 24 tumor tissues demonstrated a negative correlation between the expression of PGK1 protein and TRIM50 protein." (PMID 38993561, 2024).
cancer (5 papers, 2018 to 2024). A tumor composed of atypical neoplastic, often pleomorphic cells that invade other tissues. "Functionally, the overexpression of TRIM50 attenuated the proliferative capacity of cancer cells and indirectly influenced the invasive and migratory abilities of GC cells by suppressing the M2 polarization of TAMs." (PMID 38993561, 2024). "As expected, TRIM50 expression in cancer tissues was significantly lower compared with paired normal breast tissues detected by western blotting and qPCR." (PMID 39538371, 2024). "Importantly, these findings suggest that TRIM50 could serve as a potential novel therapeutic target for the treatment of malignant tumors." (PMID 38993561, 2024). "However, TRIM50 has been seldom reported about its biological function in cancer." (PMID 34568024, 2021). "Tripartite motif-containing 50 (TRIM50) belongs to the TRIM family and is reported to be related to numerous cancers." (PMID 36046365, 2022). "Tripartite motif-containing 50 (TRIM50) is a member of the TRIM family, but little is known regarding its expression and potential functional roles in cancer." (PMID 34568024, 2021).
TRIM50 also shares sentences with these, for which no sentence is quoted: lung carcinoma (1 paper); triple-negative breast carcinoma (1).